OAS3 (2'-5'-oligoadenylate synthetase 3)
Diseases named in the same sentence as OAS3 in open-access papers (continued):
Sharing a sentence is not in itself a finding about the gene and the disease.
viral infection (44 papers, 2008 to 2026). "2'‐5'‐oligoadenylate synthetase 2 (OAS2) gene, together with neighboring OAS1 and OAS3 gene, encodes enzymes participating in innate immunity response to viral infection." (PMID 30859738, 2019). "OAS2 and OAS3 encode a members of the 2–5A synthetase family, essential proteins involved in the innate immune response to viral infection." (PMID 29642892, 2018). "USP18, STAP1, and OAS3 are involved in anti-viral response and have been shown to be upregulated in blood or lung tissue during viral infection." (PMID 41496780, 2025). "Oas1a, Oas1g, and Oas3 play a crucial role in the innate immune response against viral infection, leading to viral RNA degradation and replication inhibition." (PMID 39408685, 2024). "OAS3 (2'-5'-oligoadenylate synthetase 3) is an enzyme activated by double-stranded RNA (dsRNA) and is essential in the innate immune response against viral infections." (PMID 39494334, 2024). "OAS1 is induced earlier than OAS2 and OAS3 during dengue virus infection, and mutations of the different OAS members had been correlated with several viral infections." (PMID 37209263, 2023). "OAS1a was found to be significantly elevated whereas OAS3 expression was reduced in the cornea of OPN KO mice post virus infection." (PMID 36685562, 2022). "OAS3 expression is also induced through the interferon signaling pathway, and the protein acts against viral infection." (PMID 34960686, 2021). "In fact, only OAS3 in the human OAS family can initiate the OAS/RNaseL pathway upon viral infection." (PMID 30587119, 2018). "Previously it was thought that OAS1, 2, and 3 were involved in activating RNase L during viral infection, until recently Li and colleagues observed that OAS3 is mainly responsible for producing the 2–5A RNase L activators." (PMID 28580319, 2017). "The OAS3 gene product is an enzyme that functions to resist viral infection via the destruction of intracellular RNA." (PMID 25345603, 2015). "OAS3 plays a role in resistance to viral infection via degradation of viral and cellular RNAs and impairment of viral replication." (PMID 20084279, 2010). "Furthermore, Wang and her colleagues also discovered a significant association of OAS3 with CIN3/cancer, including viral infections in CESC." (PMID 37735483, 2023). "It was found that OAS1 and OAS3 participated in the activation of RNase L during viral infection." (PMID 32276512, 2020). "Induction of OAS proteins by IFN and viral replication leads to synthesis of 2’5’ oligoadenylates which activate RNase L. OASs (OAS1, OAS2, OAS3) synthesize 2’-5’ oligoadenylates and activate RNase L leading to degradation of viral and cellular RNAs, thereby restricting viral infections." (PMID 30779786, 2019). "OAS3, identified in Network 1 at 24hpi, may also have an important role in T1L infection, since it has antiviral properties in other viral infections, such as dengue, tick-borne encephalitis and chikungunya virus." (PMID 23240068, 2012). "In this population-based study, we found nine genes/regions associated with CIN3/cancer, 6 of which remained significant at a FDR≤0.2 – three DNA repair genes (GTF2H4, DUT, and DMC1) and three viral infection and cell entry related genes (OAS3, SULF1, and IFNG)." (PMID 20084279, 2010). "MX1, MX2, and OAS family members OAS1, OAS2, OAS3 mediate resistance to virus infection." (PMID 18648529, 2008). "The potential role of OAS3 in the recognition of CpG- and UpA-high mutants is consistent with its demonstrated preferential role in mediating RNAseL responses to a wide range of virus infections, and the frequent inactivity of OAS1 (and OAS2) in antiviral defence." (PMID 31276592, 2019). "Previous studies have identified that following viral infection, type I IFN signaling induces the production of the OAS family consisting of OAS1, OAS2, OAS3, and OAS-like (OASL) protein." (PMID 38650851, 2024).
viral infection (continued). "For example, upregulated genes OASL, OAS1, OAS2, and OAS3 belong to the OAS family, a group of antiviral enzymes induced by type I IFNs, which can locate and bind viral dsRNA after viral infection." (PMID 36655136, 2023). "In our data, the enriched pathways were related to viral infections such as influenza A (MX1, OAS1, OAS2, OAS3, RSAD2, STAT1) and measles (MX1, OAS1, OAS2, OAS3, STAT1)." (PMID 35464437, 2022). "Previous work has identified that following viral infection, type I IFN signaling induces the production of the 2′-5′-oligoadenylate synthetase (OAS) family, which include OAS1, OAS2, OAS3, and OAS-like (OASL) protein." (PMID 28580319, 2017). "In particular, interferon stimulated pathways such as those including RSAD2, IRF7, MX1, OAS3, MDA-5, RIG-I and others are incorporated and thought to drive both innate and, to a lesser degree, adaptive immune responses to viral infection." (PMID 23326326, 2013). "Similar to the protein results, mRNA detection results showed that in the absence of viral infection, diABZI treatment significantly upregulated the mRNA level of 2,5′-oligoadenylate synthase 3 (Oas3)." (PMID 41373601, 2025). "It is speculated that viral infection can activate the JAK-STAT signaling pathway, promote cell proliferation by inducing OAS3 expression in keratinocytes, and ultimately aggravate the inflammatory response in psoriasis." (PMID 40560938, 2025). "We observed that adult patients with epileptic seizures had peripheral whole blood that included miR-654-3p, miR-323a-3p, miR-323b, miR-3283p, miR-342-5p, miR-150-5p, miR-3395p and IFIT3, IFIT1, IFI44L, OAS3, and LY6E in the pathways connected to viral infection." (PMID 36172025, 2022). "Finally, the overexpression of MX1, a well-characterized biomarker of viral infection; IFIT1, one of the top upregulated genes; and OAS1, OAS2 and OAS3, genes with a molecular function, 2-5-oligoadenylate synthase activity, identified as enriched in the DGE analyses, was confirmed by RT-qPCR." (PMID 42194954, 2026). "According to related studies, the expression level of OAS1 in anti-viral infection is higher than that of OAS2 and OAS3, and there is a high correlation between the expression of OAS1 and the other three OAS genes, which may indicate the important role of OAS1." (PMID 36162993, 2022). "While OAS3 is the primary activator of RNASEL during most viral infections, oncogenic cells failed to express ectopic OAS3 at levels that could be validated by immunoblot." (PMID 35594991, 2022). "To investigate whether the antiviral effect of C11orf83 is through OASs-RNase L system, we examined the expression of OAS family four members (OAS1, OAS2, OAS3, and OASL) at the mRNA level in HEK293 cells that only overexpressed C11orf83 but no viral infection." (PMID 28418037, 2017).
breast carcinoma (11 papers, 2018 to 2026). "OAS3 plays a critical role in antiviral action and signal transduction, and high OAS3 expression is associated with the poor prognosis of patients with breast cancer." (PMID 35592250, 2022). "Previous studies have shown that high mRNA expression of OASL and OAS3 was associated with poor prognosis in all breast cancer patients." (PMID 34616451, 2021). "High mRNA expression of OAS1 (HR = 1.5, 95%CI: 1.06–2.14, p = 0.022) and OAS3 (HR = 1.7, 95%CI: 1.19–2.42, p = 0.0029) was significantly associated with worse OS in luminal A type breast cancer patients." (PMID 32560641, 2020). "High mRNA expression of OAS1 and OAS3 were correlated with worse prognosis for all breast cancer patients, whereas OAS2 was associated with favorable prognosis." (PMID 32560641, 2020). "However, high expression of OAS1 and OAS3 was significantly associated with worse overall survival in Luminal A breast cancer." (PMID 36430510, 2022). "OAS1, OAS2, and OAS3 were significantly associated with prognosis for all breast cancer patients." (PMID 32560641, 2020). "Besides, OAS3's expression was associated with key processes such as cell cycle regulation and immune evasion, further underscoring its potential as a therapeutic target in lung and breast cancers." (PMID 41700140, 2026). "The mutational spectrum of OAS1, OAS2, OAS3, and OASL genes in breast cancer patients from the TCGA dataset was investigated using the cBioportal database." (PMID 39633486, 2024). "High mRNA expression of OAS1 and OAS3 was correlated with worse prognosis, while high mRNA expression of OAS2 was associated with better outcomes in all breast cancer patients." (PMID 32560641, 2020). "High mRNA expression of OAS1 (HR = 2.01, 95%CI: 1.26–3.18, p = 0.0026), OAS3 (HR = 1.72, 95%CI: 1.13–2.64, p = 0.011) and OASL (HR = 1.8, 95%CI: 1.17–2.77, p = 0.0066) was significantly associated with worse OS in grade 2 breast cancer." (PMID 32560641, 2020). "In summary, we found that high mRNA expression of OAS1 and OAS3 was correlated with worse prognosis in all breast cancer patients." (PMID 32560641, 2020). "Results from UALCAN and GEPIA indicated that the mRNA levels of OAS1, OAS2, OAS3, and OASL were markedly higher (p-value < 0.05) in breast cancer samples compared to normal samples, aligning with the outcomes observed in cell lines." (PMID 39633486, 2024). "Overall, these results highlight the critical roles of OAS1, OAS2, OAS3, and OASL in supporting the growth and proliferation of breast cancer cells, while also suggesting their involvement in modulating cellular migration." (PMID 39633486, 2024). "The constructed predictive model showed that OAS1, OAS2, OAS3, and OASL genes can effectively predict the overall survival of breast cancer patients." (PMID 39633486, 2024). "To further investigate the functional roles of the OAS family genes in breast cancer, we designed four siRNAs targeting OAS1, OAS2, OAS3, and OASL and transfected them into HOC1 cells." (PMID 39633486, 2024). "The results uncovered a significant correlation between the expression of OAS1, OAS2, OAS3, and OASL and all immune molecule subtypes in breast cancer." (PMID 39633486, 2024). "Our study observed significant correlations between the expression of OAS1, OAS2, OAS3, and OASL and various molecular and immune subtypes of breast cancer." (PMID 39633486, 2024). "The results revealed that breast cancer patients exhibiting increased expression of OAS1, OAS2, OAS3, and OASL genes had poor overall survival." (PMID 39633486, 2024). "Next, we validated the promoter methylation levels of OAS1, OAS2, OAS3, and OASL genes in both breast cancer and control samples utilizing the OncoDB database." (PMID 39633486, 2024). "The experimental data revealed significantly elevated mRNA levels of OAS1, OAS2, OAS3, and OASL in breast cancer cell lines relative to normal controls (p-value < 0.05)." (PMID 39633486, 2024).
breast carcinoma (continued). "In breast cancer, for instance, there is a notable upregulation of OAS genes such as OAS1, OAS2, OAS3, and OASL." (PMID 39633486, 2024). "The knockdown of OAS1, OAS2, OAS3, and OASL in HOC1 cells, validated by qRT-PCR and Western blot analyses, revealed their critical roles in breast cancer." (PMID 39633486, 2024). "The OAS family genes (OAS1, OAS2, OAS3, and OASL) were found to be significantly upregulated in breast cancer cell lines and tissues compared to normal controls." (PMID 39633486, 2024). "To investigate the correlation between the expression levels of OAS1, OAS2, OAS3, and OASL genes and the survival outcomes in breast cancer patients, we utilized the Kaplan-Meier Plotter online bioinformatics tool." (PMID 39633486, 2024). "Utilizing the TISIDB database, we explored the relationship between OAS1, OAS2, OAS3, and OASL expression in breast cancer across various immune and molecular subtypes." (PMID 39633486, 2024). "A total of five drugs, Acetaminophen, Estradiol, Cyclosporine, Calcitriol, and Seocalcitol, demonstrated the capability to potentially reduce the expression levels of OAS1, OAS2, OAS3, and OASL, suggesting their prospective use in breast cancer treatment." (PMID 39633486, 2024). "High mRNA expression of OAS2 (HR = 0.26, 95%CI: 0.1–0.67, p = 0.0027), OAS3 (HR = 0.43, 95%CI: 0.26–0.7, p < 0.001), and OASL (HR = 0.47, 95%CI: 0.27–0.83, p = 0.0078) was correlated with better OS in basal-like breast cancer." (PMID 32560641, 2020). "To establish interferon induction in breast cancer MDA-MB-231 cultured cells, we looked for interferon stimulated genes (ISG) including: OAS1, OAS3, RIG1, TLR3 and IFI16 genes." (PMID 32817625, 2020). "High mRNA expression of OAS3 (HR = 0.65, 95%CI: 0.47–0.9, p = 0.0088) and OASL (HR = 0.62, 95%CI: 0.44–0.86, p = 0.0035) was found to be correlated with better OS in grade 3 breast cancer." (PMID 32560641, 2020). "Furthermore, the findings from GEPIA revealed that the expressions of OAS1, OAS2, OAS3, and OASL genes were notably more pronounced in the advanced stages of breast cancer compared to the early stages." (PMID 39633486, 2024). "The comprehensive examination of the mutational landscape of OAS1, OAS2, OAS3, and OASL genes in breast cancer patients revealed that OAS1, OAS3, and OASL exhibited an absence of mutations in all 986 analyzed breast cancer samples." (PMID 39633486, 2024). "The findings indicated that OAS1, OAS3, and OASL genes did not exhibit mutations among the 986 analyzed breast cancer samples." (PMID 39633486, 2024). "Furthermore, our findings indicate a noteworthy negative correlation between OAS1, OAS2, OAS3, and OASL elevated gene expression and a substantial decrease in promoter methylation levels across breast cancer tissues." (PMID 39633486, 2024). "Additionally, results from HPA demonstrated a significant elevation in protein expression levels of OAS1, OAS2, OAS3, and OASL in breast cancer tissue samples as opposed to normal tissue samples." (PMID 39633486, 2024).
influenza (6 papers, 2015 to 2022). An acute viral infection of the respiratory tract, occurring in isolated cases, in epidemics, or in pandemics; it is caused by serologically different strains of viruses (influenzaviruses) designated A, B, and C, has a 3-day incubation period, and usually lasts for 3 to 10 days. "Likewise, we found that the presence of the Neandertal haplotype was associated with reduced expression levels of OAS3, particularly in PBMCs infected with influenza (P = 6.1 × 10−3) and the synthetic ligand gardiquimod (P = 2.0 × 10−4), which mimics a single strand RNA infection." (PMID 27899133, 2016). "Specifically, influenza samples maintained higher levels of type I IFN response–associated antiviral ISGs (e.g., IFITM1, IFITM2, IFITM3, OAS2, OAS3, OASL) and antigen presentation genes (e.g., HLA-DRB5, HLA-C, B2M, HLA-B, HLA-E)." (PMID 34618691, 2021). "These genes belong to a family of pattern-recognition receptors involved in innate immune responses against both RNA and DNA viruses, with OAS3 considered to be essential in reducing viral titer during Chikungunya, Sindbis, influenza or vaccinia viral infections." (PMID 36480515, 2022). "While none of these six genes were amongst the best discriminators of respiratory syncytial virus (RSV) from influenza, four of the six genes (OAS3, SEPT4, LAMP3 and RPT4) were represented in a gene list of 161 interferon-related differentially expressed genes." (PMID 25345603, 2015).
melanoma (6 papers, 2012 to 2026). A malignant, usually aggressive tumor composed of atypical, neoplastic melanocytes. "Mutation analysis highlighted high mutation frequencies of OAS3 in several cancer types, especially in endometrial cancer and melanoma." (PMID 41700140, 2026). "This study showed that patients with melanoma and kidney renal clear cell carcinoma with high OAS3 expression had a higher clinical benefit from ICB treatment (PD-1 or PD-L1)." (PMID 35592250, 2022). "In addition, the results demonstrated that high expression levels of OAS3 were associated with better PD1 OS in melanoma (Gide2019_PD1, Liu2019_PD1) and better PFS in kidney renal clear cell carcinoma and melanoma (Miao2018_ICB, Liu2019_PD1)." (PMID 35592250, 2022). "Among the top markers, OAS3 and SERPINA6 are predicted to be blood secretory by our prediction program, hence suggesting the potential feasibility in identifying diagnostic markers for melanoma through blood tests." (PMID 22295108, 2012).
cervical cancer (5 papers, 2011 to 2021). A primary or metastatic malignant neoplasm involving the cervix. "In a subsequent study by the same group, genes/regions statistically significantly associated with CIN3 or cervical cancer included viral infection and cell entry genes OAS3, SULF1, and IFNG; the DNA repair genes DU, DMC, and GTF2H4; the EVER1 and EVER2 genes." (PMID 23554684, 2011). "Until now, only OAS3 had been associated with the HPV persistence and progression of cervical cancer." (PMID 30134903, 2018). "OAS3, SULF1, DUT, and GTF2H4 SNPs were associated with HPV persistence, whereas IFNG and EVER1/EVER2 SNPs were associated with progression to cervical cancer." (PMID 23554684, 2011). "Meanwhile, according to MCC scores from the CytoHubba plugin in Cytoscape, the top 5 cervical cancer-related genes were screened out (MEF2C, CXCL16, IRF4, OAS3, PTGER3)." (PMID 34020619, 2021).
dengue virus infection (5 papers, 2012 to 2023). "In addition, other members of the OAS gene family, as OAS1 p42, OAS1 p46, and OAS3 p100 have been shown to have antiviral effects in dengue complication." (PMID 26302899, 2015).
psoriasis (5 papers, 2019 to 2025). An autoimmune condition characterized by red, well-delineated plaques with silvery scales that are usually on the extensor surfaces and scalp. "In another study based on the expression profile analysis of psoriasis vulgaris diffuse genes, OASL/OAS2/OAS3 were considered as novel hub genes associated with psoriasis." (PMID 40560938, 2025). "In patients with psoriasis, OAS3 regulates the cell cycle and enhances JAK1-STAT1 phosphorylation induced by type I interferon." (PMID 40560938, 2025). "This study suggested that during the COVID-19 pandemic, ADA, SEC, and IXE may suppress serum OAS2 and OAS3 levels in patients with psoriasis, thereby preventing psoriasis exacerbation." (PMID 38298734, 2024). "A total of 5 genes (DEFB103A, OAS3, OASL, SAMD9, STAT1) were co-identified as characteristic genes in psoriasis progression and treatment." (PMID 40560938, 2025). "In summary, the study identified a series of characteristic genes (DEFB103A, IFI16, OAS3, OASL, SAMD9, STAT1, etc.)that are highly related to the occurrence, treatment of psoriasis." (PMID 40560938, 2025). "What's more, the use of biological agents suppressed the serum OAS2 and OAS3 at low levels and elevated the serum OAS1 level in patients with psoriasis." (PMID 38298734, 2024). "For example, OAS1, OAS2, OAS3, and IFI44L appear to be down-regulated by etanercept in responders to treatment for psoriasis." (PMID 30665420, 2019). "In addition, the use of biological agents suppressed the serum OAS2 and OAS3 and elevated the serum OAS1 level in psoriasis patients." (PMID 38298734, 2024). "Additionally, the utilization of biological agents resulted in the suppression of serum OAS2 and OAS3 at low levels, along with an elevation in the serum OAS1 level among patients with psoriasis." (PMID 38298734, 2024). "Thus, serum markers of psoriasis patients using different biologics, including OAS1, OAS2, and OAS3, were also tested." (PMID 38298734, 2024). "In contrast, antiviral genes MX1, OAS3, and IFI44L were suppressed in γδ T cells in psoriasis, suggesting that these cells may be less primed to combat viral threats; alternatively, this finding could reflect an upregulation of these genes within the control group." (PMID 41181116, 2025). "In addition, the use of biological agents may suppress the serum OAS2 and OAS3 at low levels and elevate the serum OAS1 level in patients with psoriasis." (PMID 38298734, 2024).